S100A6 (S100 calcium binding protein A6)
Diseases named in the same sentence as S100A6 in open-access papers (continued):
Sharing a sentence is not in itself a finding about the gene and the disease.
glioma (7 papers, 2014 to 2025). A benign or malignant brain and spinal cord tumor that arises from glial cells (astrocytes, oligodendrocytes, ependymal cells). "Dysregulated expression of S100A6 associates with glioma progression have been reported." (PMID 36046652, 2022). "As a common abnormally expressed gene in tumors, S100A6 has been found in the lateral population of cancer stem cells (CSCs) isolated from brain tumors of transgenic mice forming glioma mouse models." (PMID 37670392, 2023). "Unfortunately, the mechanisms and signal pathways of S100A6 associated to tumor progression has, to present, not been studied in glioma." (PMID 36046652, 2022). "S100A6 has a tumor-promoting effect in a variety of cancers, and S100A6 expression may be an important factor to distinguish glioma grade, potentially in serum." (PMID 34148033, 2021). "However, the functional role and underlying mechanism of SMOC1, HIPK2, UBA52, S100A6, PPP1CB, CALD1, and TMSB4X in the occurrence and development of diffuse high-grade gliomas was still unknown." (PMID 39530009, 2024). "In gliomas, SMOC1, S100A6, CTSB, SPP1, and IGFBP2 serve as a potential therapeutic target in glioma." (PMID 39530009, 2024). "Immunofluorescence staining confirmed the presence of S100A6 and S100A4 proteins in the cancer subpopulation of primary human glioma, and their abundance was correlated with tumor grade." (PMID 37670392, 2023). "In contrast, it demonstrates a negative correlation with GMFG, S100A6, and S100A11, all of which are associated with promoting glioma progression." (PMID 38674418, 2024).
colon cancer (6 papers, 2009 to 2023). "Lamin A/C, a protein known to be involved in colon cancer, interacts with S100A6, which also provides indirect evidence that S100A6 is involved in colon cancer." (PMID 37670392, 2023). "It has been shown that S100A6 contributes to cell proliferation, migration, and adhesive properties of some cancers, such as breast, stomach, pancreas, and colon cancer." (PMID 35432196, 2022). "Co-immunoprecipitation was used to examine the interaction of endogenous CacyBP/SIP with S100A1 and S100A6 in colon cancer SW480 cells." (PMID 29534068, 2018). "In summary, we showed that S100A6 is involved in the nuclear translocation of CacyBP/SIP in a Ca2+-dependent manner in colon cancer SW480 cells." (PMID 29534068, 2018). "A link between S100A6 and colon cancer invasion has also been suggested by the observation that increased expression of S100A6 is found at the leading edges of colon cancer tissues." (PMID 19724273, 2009). "Thus, we demonstrated that S100A6 is required for the Ca2+-dependent nuclear translocation of CacyBP/SIP in colon cancer SW480 cells." (PMID 29534068, 2018).
astrocytoma (5 papers, 2004 to 2025). "Since yeast two-hybrid experiments have shown S100A6 to interact with S100B and co-localise in astrocytoma cells, we investigated the expression of both S100A6 and S100B in serial sections of prostatic adenocarcinoma of various Gleason scores and adjacent benign epithelium." (PMID 15280928, 2004). "S100A6 had the highest tag counts in oligodendroglioma (15 tags), medulloblastoma (10.4 tags) and grade II and III astrocytoma (49.1 and 55 tags, respectively)." (PMID 18781180, 2008).
breast tumour (5 papers, 2007 to 2020). "We also stained breast tumour xenografts from Severe Combined Immune-Deficiency (SCID) mice (immunodeficient mice that have impaired ability of making T or B lymphocytes) for LAMP2 and S100A6." (PMID 26658462, 2015).
cervical carcinoma (5 papers, 2012 to 2024). A carcinoma arising from either the exocervical squamous epithelium or the endocervical glandular epithelium. "In colorectal and cervical cancer, S100A6 stimulates the proliferation and migration of cancer cells through the mitogen-activated protein kinases (MAPK) and PI3K/AKT signaling pathways, respectively." (PMID 34148033, 2021). "Distinct intracellular localization of S100A6 and S100A4 was shown to be dependent on calcium concentrations in the MDA-MB231 metastatic epithelial breast adenocarcinoma cells and cervical carcinoma HeLa cells." (PMID 22727333, 2012).
colorectal adenocarcinoma (5 papers, 2000 to 2021). The most common type of colorectal carcinoma. "Until now, only two small studies have comparatively assessed the expression of S100A6 in human colorectal mucosa, primary colorectal adenocarcinomas, and liver metastases using a specific western blot analysis." (PMID 19048101, 2008). "When S100A6 expression levels in three sets of matched samples of primary colorectal adenocarcinoma (T) and liver metastasis (M) were examined, S100A6 levels were higher in M than in T in two of three cases." (PMID 10952782, 2000). "Immunohistochemical analysis using monoclonal anti-S100A6 antibody showed that 23 of 42 (55%) primary colorectal adenocarcinoma and 15 of 16 (94%) liver metastasis specimens were positively stained." (PMID 10952782, 2000). "S100A6 has previously been shown to be upregulated in colorectal adenocarcinomas." (PMID 34563043, 2021). "To study their involvement in the malignancy of human colorectal adenocarcinoma, we examined the protein expression levels of S100A6 and S100A4 in the primary colorectal adenocarcinoma (T) and paired adjacent normal colorectal mucosa (N) from 12 cases, quantitatively by Western blot analysis." (PMID 10952782, 2000). "S100A6 immunostaining of primary colorectal adenocarcinomas was significantly more intense in the invading fronts with structural atypia than in central portions with glandular structure (P< 0.0001), whereas Ki-67 staining (a growth marker) was similar in these two portions." (PMID 10952782, 2000).
diabetes (5 papers, 2014 to 2025). "The identification of promising drug targets like CA1, S100A6, and DDT further advances the precision medicine landscape in diabetes care, offering potential avenues for targeted therapeutic interventions and improved outcomes." (PMID 39850446, 2025). "We did not observe differences in the relative amount of HMGB1, S100B, S100A6 and SOD1 proteins in SN harvested from diabetic and control mice at six months after diabetes induction in our experiment (P ≥ 0.05)." (PMID 37462767, 2023).
medulloblastoma (5 papers, 2007 to 2022). A malignant, invasive embryonal neoplasm arising from the cerebellum. "For example, DNA hypomethylation resulted in reduced S100A6 and S100A10 expression in medulloblastoma while somatic methylation controlled S100A2 and S100A4 expression in the normal cerebellum, showing tissue specific regulation." (PMID 34485305, 2021). "This study demonstrates a role for the epigenetic deregulation of three members of the S100 gene family, S100A4, S100A6 and S100A10, in medulloblastoma tumourigenesis." (PMID 17579622, 2007). "Two of the genes identified by this approach, S100A6 and S100A10, were each hypermethylated in a proportion of both medulloblastoma cell lines and primary tumours (each in ∼12% of cases), but not in the normal cerebellum." (PMID 17579622, 2007). "The methylation status of CpG sites within the promoter/exon 1 regions of S100A6 and S100A2, which have previously been identified as being involved in their epigenetic regulation, was established in a panel of nine medulloblastoma cell lines by bisulphite sequencing." (PMID 17579622, 2007). "Assessment of these genes in the non-neoplastic cerebellum (from which medulloblastomas develop) revealed strong somatic methylation affecting S100A2 and S100A4, whereas S100A6 and S100A10 were unmethylated." (PMID 17579622, 2007).
viral infection (5 papers, 2012 to 2023). "In order to investigate the expression patterns of s100a4 and s100a6 under general conditions that mimic bacterial and viral infection, the immunostimulation assay was carried out in PK-15 cells by using the LPS and Poly (I:C) as the stimulators." (PMID 22330747, 2012).
epilepsy (4 papers, 2014 to 2020). A brain disorder characterized by episodes of abnormally increased neuronal discharge resulting in transient episodes of sensory or motor neurological dysfunction, or psychic dysfunction. "A recent study reported for the first time that up-regulation of S100A6 in activated astrocytes may be linked to glutamate toxicity in the hippocampus of two mouse models of brain aging and epilepsy, and in the axotomized hypoglossal nucleus of one mouse model." (PMID 24739809, 2014). "Higher S100A6 expression has been later found in rat brain in a model of epilepsy induced by status epilepticus evoked by amygdala stimulation." (PMID 32492924, 2020). "Increased S100A6 level has also been observed in the rat brain following kainic acid-induced epilepsy." (PMID 32492924, 2020). "It has been shown that in rats with induced epilepsy, the level of S100A6 protein was up-regulated in the cerebral cortex and the CA1 region of the hippocampus after 2 weeks of amygdalar stimulation." (PMID 28068373, 2017). "Increases in the levels of S100A6 mRNA have also been demonstrated in epilepsy and following traumatic brain injury." (PMID 28068373, 2017). "In the case of epilepsy and all of these other diseases, up-regulation of S100A6 was correlated with astrogliosis." (PMID 28068373, 2017). "S100A6 expression was observed in the hippocampus of mouse models of brain aging and epilepsy, and in the axotomized hypoglossal nucleus of mice." (PMID 24739809, 2014). "Moreover, the increase in S100A6 expression following epilepsy was shown to be widespread and long lasting." (PMID 32492924, 2020). "In addition, S100A6 mRNA up-regulation has been observed in cortical regions of mouse brain in which epileptiform activity was induced by blood–brain barrier breakdown, albumin or transforming growth factor β1 (TGF-β1), and following epilepsy-inducing traumatic brain injury." (PMID 32492924, 2020).
glioblastoma (4 papers, 2015 to 2025). The most malignant astrocytic tumor (WHO grade IV). "In glioblastoma, multi-omics integration demonstrated that lactylation-high clusters (marked by S100A6 expression) are not randomly dispersed but are spatially confined to hypoxic tumor cores and perinecrotic regions." (PMID 41583433, 2025).
lymph node metastasis (4 papers, 2004 to 2025). "S100A10 and S100A6 have been reported to be biomarkers for PTC with lymph node metastasis (LNM)." (PMID 40430098, 2025). "S100A10, S100A6, S100A4 and IGFBP3 have all been linked to PTC with lymph node metastasis (LNM)." (PMID 40430098, 2025). "Positive expression of S100A6 correlated with age, location, size of tumor, depth of invasion, vessel invasion, lymph node metastasis, distant metastasis and TNM stage (P < 0.05), but did not correlate with gender, differentiation or histological type (P > 0.05)." (PMID 22681645, 2012).
osteoarthritis (4 papers, 2021 to 2025). A noninflammatory degenerative joint disease occurring chiefly in older persons, characterized by degeneration of the articular cartilage, hypertrophy of bone at the margins and changes in the synovial membrane. "However, owing to the deficiency of relevant researches about S100A6 roles in osteoarthritis, its biological functions and research value remain to be fully clarified." (PMID 33942537, 2021). "Higher levels of GREM1 and S100A6, however, correlate with osteoarthritis, opposing the expression of NID2 and EDIL3." (PMID 40224957, 2025). "First of all, we investigate the relationship between S100A6 and the pathological changes of osteoarthritis." (PMID 33942537, 2021). "Immunofluorescence assay was produced to identify the rat chondrocyte sample and western blots assay was detected the expression changes of S100A6 between control group and osteoarthritis model which induced by interleukin‐1β." (PMID 33942537, 2021). "We determined the expression of S100A6 decreased in osteoarthritis model, the relative expression level in osteoarthritis model was about 0.5 fold compared with control group." (PMID 33942537, 2021). "Studies have shown that S100A6 participates in the progression of osteoarthritis." (PMID 38877413, 2024). "In conclusion, this study showed the S100A6 was related to the inflammation of osteoarthritis." (PMID 33942537, 2021). "The influence of S100A6 on inflammatory reaction of osteoarthritis was detected by RT‐PCR." (PMID 33942537, 2021). "S100A6 plays a significant role in the progression of osteoarthritis." (PMID 33942537, 2021). "Finally, our findings corroborate the experimental hypothesis and support that S100A6 is a potential therapeutic target for osteoarthritis." (PMID 33942537, 2021). "More importantly, the apoptosis triggered by S100A6 can be offset by the PI3K/AKT pathway inhibitor and activator (LY294002 and IGF‐1), the values of Caspase‐3 activity and apoptosis index became close to the untreated osteoarthritis group." (PMID 33942537, 2021). "Through adenovirus transfection we revealed that the inflammatory factors of osteoarthritis (interleukin‐6 and matrix metalloproteinase‐13) showed a negative correlation with the S100A6 expression." (PMID 33942537, 2021). "According to recent research, there have been no studies to clarify the mechanism and function of S100A6 on osteoarthritis at a cellular level." (PMID 33942537, 2021).
systemic sclerosis (4 papers, 2021 to 2023). A chronic disorder, possibly autoimmune, marked by excessive production of collagen which results in hardening and thickening of body tissues. "In conclusion, this study confirmed circulatory cytohesin 2, calumenin and S100A6 as biomarkers in Ssc patients and found associations between the serum levels of these biomarkers and clinical characteristics, especially with severe cutaneous involvement (necrosis and diffuse sclerosis)." (PMID 34063287, 2021). "Serum calumin, S100A6, and cytokinin 2 have been confirmed as biomarkers in patients with systemic sclerosis with skin involvement, and S100A6 is related to the number of active digital ulcers." (PMID 37670392, 2023). "S100A6 has been demonstrated to fulfill a role in other inflammatory autoimmune diseases such as primary biliary cholangitis and systemic sclerosis of the lung, consistent with our observations." (PMID 37185712, 2023). "S100A6 has been shown to be increased in the serum of patients with systemic sclerosis, and this has been correlated with disease activity." (PMID 36748983, 2023). "Also, very high levels of S100A6 were found in Ssc patients, which points out the fact that this specific molecule could be a potential future therapeutic target at least for prevention of digital ulcer development/aggravation." (PMID 34063287, 2021).
astrocytic tumor (3 papers, 2020 to 2022). A glial tumor of the brain or spinal cord showing astrocytic differentiation. "A previous study has been shown to clearly distinguish between low-grade (WHO grade I and II) and high-grade (WHO grade III and IV) astrocytic tumors after altering the level of S100A6 protein expression." (PMID 36046652, 2022). "In an earlier study, changes in S100A6 protein expression levels were markers of differentiation between low-grade astrocytic tumors." (PMID 34148033, 2021). "While S100A6 protein expression enabled a clear distinction between low (WHO grade I and II) and high (WHO grade III and IV) grade astrocytic tumors." (PMID 31968004, 2020).
autoimmune encephalitis (3 papers, 2019 to 2023). Inflammation of the brain secondary to an immune response triggered by the body itself. "Further investigation of the effect of S100A6 can improve our understanding of the pathogenesis of autoimmune encephalitis and serve as a potential therapeutic target." (PMID 36748983, 2023). "We demonstrated that S100A6 participated in promoting B lymphocyte infiltration through the blood‐brain barrier in patients with autoimmune encephalitis." (PMID 36748983, 2023). "The genome-wide methylation array has identified a few hypomethylated immune-related genes, amongst them S100A6 which shows up-regulation in autoimmune encephalitis patients." (PMID 36970516, 2023).
brain injury (3 papers, 2014 to 2025). Acute and chronic (see also brain INJURIES, CHRONIC) injuries to the brain, including the cerebral hemispheres, CEREBELLUM, and brain STEM. "Fang and colleagues showed that the recovery of the cognitive function of rats with traumatic brain injury was related to the re-elevation of S100A6 mRNA levels in the hippocampus." (PMID 31440382, 2019). "Importantly, S100A6 expression is tightly positively correlated with cognitive function recovery in a rat model of traumatic brain injury, implicating the regulatory role of S100A6 in cognition." (PMID 40882002, 2025). "In a rat model of traumatic brain injury (TBI), we investigated changes in cognitive function and S100A6 expression in the hippocampus." (PMID 24739809, 2014).
cholangiocarcinoma (3 papers, 2016 to 2023). A carcinoma that arises from the intrahepatic biliary tree (intrahepatic cholangiocarcinoma) or from the junction, or adjacent to the junction, of the right and left hepatic ducts (hilar cholangiocarcinoma). "Through proteomic analysis of tumor interstitial fluid, S100A6 was found to be a potential risk marker for screening cholangiocarcinoma; however, it was difficult to obtain test samples." (PMID 37670392, 2023). "In summary, our data suggest that in contrary to other gastrointestinal cancers, measurement of S100A6 is unsuitable as a diagnostic serum biomarker in patients with cholangiocarcinoma." (PMID 27709523, 2016). "Serum S100A6 has a relatively good diagnostic capacity for cholangiocarcinoma." (PMID 34063287, 2021). "In light of our findings that S100A6 concentrations might be indicative for an impaired prognosis, our results indicate that measurement of circulating S100A6 levels could be considered as a novel element in the diagnostic algorithm of patients with cholangiocarcinoma." (PMID 27709523, 2016). "Despite the emerging role of S100A6 in the pathophysiology of different (gastrointestinal) cancers, no data on the potential use of this ligand as a biomarker for cholangiocarcinoma are available." (PMID 27709523, 2016). "In accordance with this finding, we showed that S100A6 is significantly overexpressed in human and murine CCA tissue samples, corroborating a pathophysiological role of S100A6 in cholangiocarcinoma." (PMID 27709523, 2016). "Thus, future studies combining prospective clinical trials and experimental animal models are needed to further establish S100A6 measurements in the diagnosis of cholangiocarcinoma and to define the exact role of S100 family members in the pathophysiology of this devastating disease." (PMID 27709523, 2016). "Similarly, we did not detect a significant alteration in S100A6 serum levels in cholangiocarcinoma, while an up-regulation was described in other gastrointestinal cancers." (PMID 27709523, 2016). "However, up to now, serum concentrations of S100A6 have not been analyzed in patients with cholangiocarcinoma (CCA)." (PMID 27709523, 2016).
clear cell renal cell carcinoma (3 papers, 2015 to 2024). "In this study, we have demonstrated that highly elevated S100A6 regulated clear cell renal cell carcinoma growth and progression." (PMID 25760073, 2015). "In clear cell renal cell carcinoma, S100A6 (Calcyclin), as an oncogenic protein, negatively regulates CXCL14 expression, and knockdown of S100A6 promotes CXCL14-mediated apoptosis and promotes tumour progression." (PMID 26733763, 2016). "Together, these results suggest that elevated S100A6 enhances tumorigensis and suppresses CXCL14-induced cell apoptosis in clear cell renal cell carcinoma." (PMID 25760073, 2015).